BRCA1 (BRCA1 DNA repair associated)
Diseases named in the same sentence as BRCA1 in open-access papers (continued):
Sharing a sentence is not in itself a finding about the gene and the disease.
tumor (continued). "Moreover, tumor testing for BRCA1/2 mutations is a cost-effective method of triaging women with EOC for genetic counseling and a confirmatory germline test to identify BRCA1/2 mutation carriers." (PMID 34202525, 2021). "To determine whether Pdgfrβ and Pkcα activity represented therapeutic target in BRCA1-deficient tumors, we treated p18−/−;Brca1MGKO tumor cells with a PDGFR Inh III and PKCα inhibitor, Ro-31-8220." (PMID 33478572, 2021). "Thus, upregulation of multisignaling triggered by FGFR2 activation collaborated with Brca1 deficiency creates an immunosuppressive environment that enhances tumor progression." (PMID 34514747, 2021). "Further complicating the interpretation of the results, a recent study indicates that BRCA1-mutated tumors (n = 17) have a more immunosuppressed tumor microenvironment as compared to BRCA1 wild-type tumors, as evidenced by higher expression of immunoregulatory and suppressive genes." (PMID 34067105, 2021). "However, in patients who harbored a germline pathogenic BRCA1/2 mutation, only 70% of these germline mutations were identified with tumor testing, while 30% of germline mutations were missed, due to either technical or interpretative errors." (PMID 34073818, 2021). "Illumina 450k methylation data from the TCGA database was selected for tumours of the TNBC subtype based on both the Basal PAM50 molecular signature as well as ER, PR and HER2-negative histological status and data from tumours with BRCA1 mutations were also analysed." (PMID 34135468, 2021). "Notably, 36% (n = 11) of p18−/−;Brca1MGKO and 50% (n = 6) of p16−/−;Brca1MGKO tumors, but no p18−/− tumors, metastasized to the lung, consolidating the role of loss-of-function of Brca1 in promoting tumor metastasis." (PMID 33478572, 2021). "The University Health Network (UHN) Genome Diagnostics laboratory was one of two initially funded provincial laboratories, providing a unique opportunity to evaluate the detection rate of tumor BRCA1/2 variants in a large, population‐based, tumor testing program." (PMID 33030818, 2021). "However, routine BRCA diagnostic approaches cannot reveal the exact time and origin of BRCA1/2 mutation formation, and thus, the fine details of their contribution to tumor progression remain less clear." (PMID 34068254, 2021). "The tumor-node-metastasis (TNM) stage of BRCA1 p.Ile1824fs mutation carriers was stage III." (PMID 34570441, 2021). "The second multivariate survival model was applied to test the correlation between time from initial diagnosis to each subsequent relapse and BRCA1 mutation/promoter methylation status, assuming the independency of subsequent relapses and all originating from the primary tumor." (PMID 34601813, 2021). "Germline testing is also recommended for patients with pathogenic/likely pathogenic BRCA2 mutations identified through tumor sequencing and should also be considered in patients with alterations in other genes linked to cancer predisposition syndromes (i.e., BRCA1, ATM, MMR genes)." (PMID 33625671, 2021). "Therefore, given that BRCA1/2 mutated tumor cells have defective HR activity, the collapsed replication forks are unable to be repaired and cell death occurs." (PMID 34778062, 2021). "It is possible that there are inherent differences in response to PARPis based on whether tumours have a BRCA1 or BRCA2 mutation." (PMID 34445211, 2021). "Breast cancer type 1 susceptibility protein, encoded by the BRCA1 gene, is an 1863 aa long protein acting as a tumor suppressor which is involved in many different cellular processes like DNA repair mechanisms, DNA damage response and transcriptional regulation." (PMID 34395585, 2021).
tumor (continued). "Several studies indicate that loss of BRCA1 in breast epithelial cells may substantially affect stromal cells residing in the TME which in turn can enhance the metastatic potential of BRCA1-deficient tumor cells." (PMID 33540843, 2021). "This is further proof that detected pathogenic BRCA1 is a driver mutation in these tumours." (PMID 33808557, 2021). "In fact, BRCA1-mutated tumor cells that retain some BRCA function may be especially prone to this mechanism of PARPi-resistance." (PMID 34439286, 2021). "Therefore, it is clinically relevant to determine the frequency of HR deficiency in those tumor types as well, which are rarely associated with germline BRCA1/2 mutations." (PMID 34145376, 2021). "Besides the BRCA mutations per se, proteins encoded by alternative BRCA1 mRNA transcript can alter tumor microenvironment." (PMID 33540843, 2021). "Furthermore, the tumor stroma of BRCA1/2 mutated patients was found to be severely altered and to promote tumor growth and dissemination." (PMID 34228231, 2021). "Several studies have implicated NFκB in BRCA1-associated tumor development." (PMID 33893322, 2021). "Furthermore, we found that overexpression of BRCA1 in these cells induced expression of CDH1 (encoding E-cadherin) while inhibiting expression of FOSL1 (encoding FRA1) and VIM, consistent with our finding that deficiency of Brca1 induced EMT in tumor cells." (PMID 33478572, 2021). "Notably, tumor cells with BRCA1 or BRCA2 dysfunction are susceptible to poly(ADP-ribose) polymerase (PARP) inhibitors." (PMID 33397362, 2021). "Additionally, factors such as interleukin 6 (IL-6) and prostaglandin E2 released by the tumor cells stimulate aromatase expression in BRCA1-mutated stromal adipose cells which further enhances estrogen dependent growth of these tumor cells." (PMID 35008272, 2021). "Consequently, these malignancies are characterized by tumor-selective BRCA1/2 deficiency, down-regulation of DNA double-strand break repair and high-level chromosomal instability." (PMID 34454564, 2021). "Interestingly, depletion of COBRA1 decreased R-loop accumulation that occurs when BRCA1 is mutated, and this partially inhibited BRCA1-deficiency driven tumour formation." (PMID 33755171, 2021). "Additionally, these data also indicate that activation of Pkcα and its downstream target Fra1 is dependent on Pdgfrβ signaling, and Pdgfrβ signaling is required for maintaining the mesenchymal traits in Brca1-deficient tumor cells." (PMID 33478572, 2021). "As Fgfr2 activation enhances Brca1‐deficient tumor formation, we explored whether Fgfr2 inhibition is a viable therapeutic option for Brca1‐associated tumors." (PMID 34514747, 2021). "Alterations in the tumor microenvironment might be among the important mechanisms underlying the growth and progression of BRCA1-deficient tumors." (PMID 35008272, 2021). "Studies have shown that intricate interaction between BRCA1-deficient tumor cells and the surrounding stroma may also be manifested in promoting endothelial cell survival and vascularization." (PMID 33540843, 2021). "Several studies have reported that the crosstalk between BRCA1-deficient tumor cells and adjacent stromal cells could promote cell survival and migration." (PMID 35008272, 2021). "In particular, we focused on sample adequacy, failure rate and mutation rate of BRCA1/2 tissue testing, pointing out some pre-analytical and analytical parameters impacting on the molecular analysis, such as formalin fixation, tumor representativeness and DNA fragmentation and concentration." (PMID 34200245, 2021). "This study suggests that BCT may be an option for patients who carry a BRCA1/2 variant when the tumor is clinically appropriate for this procedure." (PMID 33890992, 2021).
tumor (continued). "Several studies have shown that PARP inhibitors might be a promising therapeutic strategy for TNBC patients with BRCA1/2 mutations, which can lead to the failure of double strand break repair, accumulation of genomic instability, and eventual tumor cell death." (PMID 33628586, 2021). "A high γδ T cell density (>6.625 γδ T cells/mm2) was associated with younger age (p = 0.008), higher tumor histological grade (p = 0.002), adjuvant chemotherapy (p = 0.010), BRCA1 promoter methylation (p = 0.010), TIL density (p < 0.001), and PD-L1 (p < 0.001) and PD-1 expression (p = 0.040)." (PMID 33673133, 2021). "Besides the identification of BRCA1/2 pathogenic variants, the analysis of tumor tissues can have other advantages." (PMID 34200245, 2021). "Furthermore, we conducted in vivo treatment of TM00091 PDX tumours, which carry two BRCA1 point mutations (Q356R and C61G), with NOTCH1 hyperactivation." (PMID 32591500, 2020). "Accurately identifying the missense mutations is of great help to alleviate the loss of protein function and structural changes, which might greatly reduce the risk of disease for tumor suppressor genes (e.g., BRCA1 and PTEN)." (PMID 33408741, 2020). "CD44+/CD24−/low phenotype was associated with BRCA1+ and basal-like tumor status." (PMID 32316333, 2020). "The hypothesis of an inhibiting combination of ABT-888 with CTLA-4 in BRCA1-deficient tumors is demonstrated by tumor regression and prolonged overall survival." (PMID 33324554, 2020). "Additionally, the presence of a large, independent cohort of BRCA1/2 mutation carriers in the validation cohort provides strong evidence to support the increased prevalence of MF/MC tumours in BRCA2 mutation carriers." (PMID 32022473, 2020). "Additionally, we found that there is a significant association between BRCA1 immunoexpression and graded tumours, mostly grade III (49.4%)." (PMID 32334465, 2020). "G4 binders may efficiently target tumours carrying mutations in the DNA damage response, such as BRCA1 and BRCA2." (PMID 32098397, 2020). "As homologous recombination repair (HRR) pathway is impaired in BRCA1-mutated tumor cells, PARP inhibition in these cells can lead to the accumulation of DNA damage and ultimately induce cell death because of impaired DNA damage repair (DDR) from both base-excision repair (BER) and HRR dysfunctions." (PMID 33282730, 2020). "Collectively, our data may represent a new therapeutic approach for GC thought co‐inhibition of c‐MET and PARP, especially for patients with BRCA1/2 deficiency tumours." (PMID 32686903, 2020). "Considering the frequencies of the variants observed in our study and the limitations of NGS, we recommend performing a specific blood test for the detection of the three most common variants in our population prior to tumor screening of the entire coding regions of BRCA1 and BRCA2 by NGS." (PMID 32850417, 2020). "Hypermethylation may be an early event in tumor development that progress along a common pathway with BRCA1-mutated disease, representing a promising DNA-based biomarker for early-stage TNBC." (PMID 32719340, 2020). "Interestingly, five samples clustered with BRCA1-associated tumours (fallopian or ovarian), the remaining seven clustered with normal fallopian tubes with no pathogenic variant." (PMID 33081408, 2020). "Altered BRCA1 expression is significantly associated with advanced tumour grade and stage." (PMID 32334465, 2020). "Importantly, the focal tandem duplications are distinct from duplications in BRCA1-deficient, cyclin E1-amplified and other HR/DNA repair-deficient tumours." (PMID 34316683, 2020). "The BRCA1 mutation group had more tumor-infiltrating lymphocytes, thus suggesting that the status of BRCA mutations could influence the immunological microenvironment sufficiently to eventually drive the specific characteristics of disease presentation." (PMID 32131779, 2020). "Additionally, in BRCA1/2-deficient tumour cells, higher sensitivity to PARP inhibition can be observed." (PMID 31940791, 2020).
tumor (continued). "Many laboratories are now performing BRCA1/BRCA2 testing in formalin-fixed paraffin-embedded (FFPE) tumor samples to detect germline and somatic variants to identify, in a single test, those patients with somatic and germline variants who are most likely to benefit from PARPi therapy." (PMID 33008098, 2020). "Thus, immune status is important in explaining variation in DFS and OS across multiple cohorts even when patient age, tumor stage, BRCA1/2 somatic mutational status, tumor cytoreduction, and COL2A1 expression is known." (PMID 32156016, 2020). "Other contributors to MSI status may include tumor mutational burden, which is a measure of nonsynonymous mutations in tumor cells, and BRCA1 mutation status." (PMID 33256070, 2020). "Usually, in tumor cells with BRCA1 and BRCA2 mutations or defects, the inhibition of the PARP enzyme can lead to the accumulation of single-strand DNA breaks, owing to the HR repair pathway being blocked, which causes further double-strand DNA breaks and finally results in the death of tumor cells." (PMID 31963730, 2020). "The breast cancer susceptibility genes, BRCA1/2, are critical tumor suppressor genes." (PMID 32950050, 2020). "It is consistent with the hypothesis that in response to PARP inhibitor therapy or platinum chemotherapy, the tumor acquired a mechanism to activate HR despite retaining BRCA1 deficiency, which can then be blocked with ATR inhibition." (PMID 32568634, 2020). "Therefore, given that BRCA1/2 mutated tumor cells have disrupted HR activity, the collapsed replication forks are unable to be repaired and cell death occurs." (PMID 33015058, 2020). "Importantly, the identification of an germline-associated BRCA1/2-mutated tumor indicates not only an underlying germline defect (in the patient and perhaps also in her family members), but also implies certain important prognostic and treatment connotations." (PMID 33117676, 2020). "This might suggest that the association observed for BRCA1 carriers is driven by screening-induced diagnoses of indolent tumours, but caution is needed in the interpretation as the sample size used for this subgroup analysis was small." (PMID 31495749, 2020). "Under the assumption that BRCA1/BRCA2 germline variants induce recognizable effects on tumor transcription, we assessed whether tumors from BRCA1/BRCA2 carriers have homogeneous gene-expression profiles." (PMID 32997669, 2020). "Herein, we sought the frequency of BRCA1 promoter hypermethylation, its tumor phenotype compared to tumors with BRCA1 inactivating genetic variants (somatic or germline, BRCA1-null), and its association with clinicopathological variables, molecular subtypes, and patient outcomes in early-stage TNBC." (PMID 32719340, 2020). "Signature 3 was more common among basal-like tumours, and is associated with mutations in the BRCA1 and BRCA2 genes and defective double-strand break repair by homologous recombination, suggesting a link between this erroneous repair mechanism and basal-like tumour development." (PMID 32164620, 2020). "Exploiting synthetic lethality with PARP inhibitors in cells that are BRCA1/2 deficient may be a promising strategy to target tumours that present a high level of R-loops." (PMID 32098397, 2020). "Tumours suppressor genes such as BRCA1/2 are closely associated with the DNA repair pathway." (PMID 32686903, 2020). "A simple IHC assay to monitor BRCA1 deficiency directly in tumor biopsies could be more convenient and affordable." (PMID 32290274, 2020). "As tumor suppressor genes, loss-of-function mutations in BRCA1/2 may lead to the accumulation of DNA double-strand breaks and result in genomic instability and tumor formation." (PMID 33054725, 2020).
tumor (continued). "Tumor BRCA1/2 variant status was determined for 276 patients (251 complete reports with fully sequenced BRCA1 and BRCA2 genes, 25 indeterminate reports with at least one failed exon), of which 17.4% (48/276) had a pathogenic/likely pathogenic variant and 8.3% (23/276) carried a VUS." (PMID 33233347, 2020). "To further understand how tumors evolve from premalignant mammary glands to PTs and metastases due to copy number changes upon the loss of Brca1, we analyzed all cells based on the tumor developmental stages in mice in the following order: VWMG, VMMG, 476WMG, 476MMG, 476PT, 153PT, and 153LMT." (PMID 32978388, 2020). "A similar trend was previously reported in mouse embryonic fibroblasts, suggesting that BRCA1/53BP1‐deficient, olaparib‐resistant tumours may be also more responsive to cisplatin in the clinic." (PMID 31273933, 2019). "Additionally, the drug is currently being tested in several clinical trials in different tumor entities with underlying mutations in BRCA1/2 and other genes involved in DDR." (PMID 31029168, 2019). "RANKL expression was elevated in OC tissue, particularly in BRCA1/2 mutated tumours." (PMID 31181781, 2019). "Interestingly, in this cohort, a high proportion of IDHWT tumours was impacted by BRCA1 (18%) and BRCA2 (18%) mutations." (PMID 32082376, 2019). "Furthermore, we applied the BRCA1/2 CNV calling-pipeline to the data generated by NGS analysis of twelve FFPE tumor samples with known germline variants (P01–13)." (PMID 31029168, 2019). "We present novel results on the differences in point mutation, DNA methylation, and structural variation in BRCA1/2 mutated tumors, and identify specific genes including known tumor suppressors that are frequently damaged by structural variation in these tumors." (PMID 31182087, 2019). "The presence of structural variants disrupting tumor suppressor genes supports the hypothesis that BRCA1/2 tumors may arise due to DNA repair deficiency leading to structural variation." (PMID 31182087, 2019). "Furthermore, the BRCA1-reconstituted tumor cells are more sensitive to the histone deacetylase (HDAC) inhibitor-induced loss of stemness than the BRCA1-deficient cells are." (PMID 31273285, 2019). "In addition, a panel of five serum tumor markers combined with BRCA1/2 mutation status showed a good performance in lymph node metastasis prediction (AUC = 0.843)." (PMID 30972954, 2019). "Interestingly, an analysis of tumor biopsies revealed an association between the methylation of BRCA1 or RAD51C and high LOH, with positive impact on ORR (52.4% and 75%, respectively) and PFS (7.4 months and 11.1 months, respectively)." (PMID 31109041, 2019). "In addition, it has been shown that BRCA1, a tumor suppressor gene well established to be associated with breast and ovarian cancer, prevents tumor formation through heterochromatin mediated silencing." (PMID 31406262, 2019). "As in the case of tumours deficient in BRCA1/BRCA2, the deficient DNA repair in RECQL-deficient tumours could increase their sensitivity to other drugs blocking compensatory DNA repair mechanisms." (PMID 30610487, 2019). "Although not statistically significant, this difference may be related to the favorable prognosis and platinum-sensitivity of tumor with BRCA1/2 mutations." (PMID 31653094, 2019). "This signature may contribute to altered responses to anti-tumor immunity in BRCA1-mutated cells or tumors." (PMID 31840082, 2019). "Importantly, low or undetectable BRCA1 expression was observed across all tumor samples, suggesting BRCA deficiency was retained in our in vivo model." (PMID 31117198, 2019).